RGS18 (regulator of G protein signaling 18)
Description:
Inhibits signal transduction by increasing the GTPase activity of G protein alpha subunits thereby driving them into their inactive GDP-bound form. Binds to G(i) alpha-1, G(i) alpha-2, G(i) alpha-3 and G(q) alpha.
Synonyms: RGS13
Tractability: Antibody: its Gene Ontology location is reachable by antibodies, with high confidence. PROTAC: its protein half-life has been measured.
Gene: Protein-coding gene on chromosome 1 (192,158,462 to 192,185,815, forward strand). Ensembl gene ENSG00000150681.
Subcellular location: Cytoplasm
Subcellular location (Human Protein Atlas): Golgi apparatus
Pathways (Reactome):
Signal Transduction: G alpha (i) signalling events; G alpha (q) signalling events
Gene Ontology:
Molecular function: protein binding; GTPase activity; GTPase activator activity
Biological process: G protein-coupled receptor signaling pathway; negative regulation of G protein-coupled receptor signaling pathway
Cellular component: cytoplasmic side of plasma membrane; plasma membrane; cytoplasm
Genetic constraint (gnomAD): Loss-of-function variants: 9 observed, 10.09 expected, observed/expected ratio (o/e) 0.89, 90% interval 0.54 to 1.54. The upper end of that interval is the gene's LOEUF score, 1.54, which puts it in group 6 of 6, group 1 being the genes least tolerant of losing a copy. Missense variants: 124 observed, 126.97 expected, observed/expected ratio (o/e) 0.98, 90% interval 0.84 to 1.13. Synonymous variants: 38 observed, 40.33 expected, observed/expected ratio (o/e) 0.94, 90% interval 0.73 to 1.24.
Homologues: Orthologues: chimpanzee RGS18 (99% identical), macaque RGS18 (98% identical), dog RGS18 (91% identical), pig RGS18 (85% identical), mouse Rgs18 (84% identical), guinea pig RGS18 (83% identical), rat Rgs18 (83% identical), rabbit RGS18 (74% identical), tropical clawed frog rgs18 (51% identical). Paralogues in human: RGS3 (36% identical), RGS2 (35% identical), RGS5 (35% identical), RGS16 (34% identical), RGS4 (34% identical), RGS8 (33% identical), RGS1 (31% identical), RGS21 (31% identical), RGS12 (29% identical), RGS20 (29% identical), RGS19 (27% identical), RGS17 (26% identical), and 11 more.
Diseases named in the same sentence as RGS18 in open-access papers:
RGS18 is named in the same sentence as 20 diseases in open-access papers, as found by Europe PMC text mining. Sharing a sentence is not in itself a finding about the gene and the disease. The quoted sentences say what the papers report.
thrombosis (4 papers, 2014 to 2024). "With regards to the role of the other RGS proteins in platelet function, we have recently shown that RGS18 deletion enhances platelet function and increases the risk of thrombosis." (PMID 27829061, 2016). "Sentinel variants at PEAR1 and RGS18 were associated with thrombosis risk through a whole genome sequencing, which provide insights regarding the mechanism by genetics may influence cardiovascular disease risk." (PMID 38166912, 2024). "To determine whether RGS18 deficiency affects platelet function in vivo, we used the silk thread arterio-venous shunt thrombosis model, which has been characterized as a “mixed” thrombosis model in rats." (PMID 25405900, 2014). "Sentinel variants at RGS18 and PEAR1 are associated with thrombosis risk and increased gastrointestinal bleeding risk, respectively." (PMID 34131117, 2021).
Arterial thrombosis (1 paper, 2021). The formation of a blood clot inside an artery. "The minor allele (C) of RGS18 at rs1175170, is associated with arterial thrombosis/embolization in both EAs and AAs in the BioVU BioBank." (PMID 34131117, 2021).
atherosclerosis (1 paper, 2017). A disease characterized by the build-up of fatty material and calcium deposition in the arterial wall resulting in partial or complete occlusion of the arterial lumen. "Thus, the RGS18 effect on platelets is mediated through calcium homeostasis and therefore genetic interactions between RGS18 and RYR3 gene are possible, and may play a substantial role in atherosclerosis as platelets are involved in its inflammatory response." (PMID 29206233, 2017).
cervical cancer (1 paper, 2021). A primary or metastatic malignant neoplasm involving the cervix. "Therefore, plasma exosomal RGS18 may be more associated with cervical cancer development and progression than the other three mRNAs (KIF2A, ARL6IP5, and DAPP1)." (PMID 34827689, 2021). "The expression of CXCL5 and KIF2A was upregulated in various cancer tissues, including cervical cancer; additionally, the expression of RGS18 in the tissues of patients with ovarian cancer was also upregulated." (PMID 34827689, 2021). "The decrease in plasma exosomal RGS18 in the cancer group may be attributed to the absorption of RGS18 by cervical cancer cells." (PMID 34827689, 2021). "In particular, tumor-related platelet activation by downregulation of RGS18 and an immune suppression by upregulation of both SNORA12 and SNORD97 may be essential mechanisms for cervical cancer development and progression." (PMID 34827689, 2021).
gastric cancer (1 paper, 2022). A primary or metastatic malignant neoplasm involving the stomach. "For gastrointestinal cancer, the prognostic value of CEBPA-DT was illustrated along with several other lncRNAs (INHBA-AS1, AK001058, UCA1, PPBP, and RGS18) in early gastric cancer." (PMID 36471363, 2022).
HCMV infection (1 paper, 2017). "Network analysis of the differentially expressed genes in cord DCs, revealed among the downregulated genes after 16 h of HCMV infection several GPCRs with pro-inflammatory response function (ADORA3, ARRB1, C5AR1, CXCR4, GPR34, GPR183, GRK3, and RGS18)." (PMID 28993767, 2017). "In addition to these, HCMV infection of cord DCs resulted in a suppression of several other GPCRs [including GPR68, GPR183 (EBI2), and GPR146] that, together with C5AR1, CXCR4, and RGS18, have been shown to be highly enriched in unstimulated macrophages and dendritic cells." (PMID 28993767, 2017).
Insulin resistance (1 paper, 2022). Increased resistance towards insulin, that is, diminished effectiveness of insulin in reducing blood glucose levels. "Finally, the associations of RGS8, RGS13, RGS18, and RGS21 with insulin secretion or insulin resistance need to be further investigated." (PMID 36497154, 2022).
pancreatic ductal adenocarcinoma (1 paper, 2024). An infiltrating adenocarcinoma that arises from the epithelial cells of the pancreas. "In pancreatic ductal adenocarcinoma, CTCs increase the expression of regulator of G-protein signaling 18 (RGS18) under the influence of platelets, and RGS18 can upregulate human leukocyte antigen-E (HLA-E) expression via the AKT-GSK3β-CREB signaling pathway." (PMID 38427120, 2024).
Splenomegaly (1 paper, 2014). Abnormal increased size of the spleen. "We consistently did not observe any splenomegaly in the RGS18-/- mice (data not shown)." (PMID 25405900, 2014).
Thrombocytopenia (1 paper, 2014). A reduction in the number of circulating thrombocytes. "Finally, RGS18 deficiency was correlated to a defect of platelet recovery in vivo under acute conditions of thrombocytopenia." (PMID 25405900, 2014). "Moreover, RGS18 deficiency induces a chronic thrombocytopenia in mice and a defect in platelet recovery and formation after acute thrombocytopenia." (PMID 25405900, 2014). "Finally, RGS18 was shown to display a thrombocytopoietic activity, as revealed by deficient platelet recovery in RGS18-/- mice under acute thrombocytopenia conditions." (PMID 25405900, 2014). "Thus, we first examined if the observed thrombocytopenia in RGS18-/- mice could be caused by a splenic sequestration of the platelets." (PMID 25405900, 2014). "In addition, RGS18-/- mice presented a mild thrombocytopenia, accompanied with a marked deficit in MK number in the bone marrow." (PMID 25405900, 2014). "In addition, RGS18-/- mice present a mild thrombocytopenia, accompanied by a reduced number of megakaryocytes (MK) in their bone marrow." (PMID 25405900, 2014). "It is interesting to note that Louwette and colleagues recently reported that lentiviral RGS18 overexpression during in vitro differentiation of mouse Sca1+ hematopoietic stem cells induced an increase in MK proliferation and that RGS18 depletion in zebrafish resulted in thrombocytopenia." (PMID 25405900, 2014).
tumor (4 papers, 2021 to 2025). "This may result in the promotion of tumorigenesis and tumor progression by facilitating tumor-associated platelet activation, and the presence of RGS18 in the tumor may contribute to sustained blood platelet concentration through its transfer to hematopoietic stem cells." (PMID 34827689, 2021). "A previous study on the RNA expression of tumor-educated platelets (TEPs) revealed that the expression level of both RGS18 and LINC00989 was lower in platelets from cancer patients than in those from healthy donors." (PMID 34827689, 2021). "Importantly, it has recently been shown that circulating tumour cells are protected from NK-cell mediated clearance via NKG2A:HLA-E interactions, with HLA-E expression promoted by platelet-derived RGS18 and NKG2A blockade able to restore NK function and prevent tumour metastasis in vivo." (PMID 38223411, 2024).
cancer (2 papers, 2021 to 2025). A tumor composed of atypical neoplastic, often pleomorphic cells that invade other tissues. "We performed correlation analysis of these six genes (PTPRC, TLR8, PLEK, NCKAP1L, RGS18 and CLEC12A) with GPR141 in pan-cancer." (PMID 40959105, 2025). "The results showed that PTPRC, TLR8, PLEK, NCKAP1L, RGS18 and CLEC12A displayed strong correlation with GPR141 in most cancer types." (PMID 40959105, 2025). "Among the four selected snoRNAs, the combination of SNORD97 with both RGS18 and SNORA12 was the most appropriate for distinguishing between the normal and cancer groups using the MDS plot, heatmap, and ROC curve analyses." (PMID 34827689, 2021). "The combination of miRNA (miR-142-3p), mRNAs (CXCL5, KIF2A, RGS18, APL6IP5, and DAPP1), and snoRNAs (SNORD17, SCARNA12, SNORA6, SNORA12, SCRNA1, SNORD97, SNORD62, and SNORD38A) clearly distinguished the normal samples from the cancer group samples." (PMID 34827689, 2021).
hematological diseases (1 paper, 2014). "From a clinical perspective, it is not clear whether increasing RGS18 function could protect from cardiovascular or hematological diseases." (PMID 25405900, 2014).
RGS18 also shares sentences with these, for which no sentence is quoted: Anxiety (1 paper); cardiac arrest (1); cardiovascular disease (1); cerebrovascular disease (1); leprosy (1); oral cancer (1); ovarian carcinoma (1).